VCAN (versican)
Description:
May play a role in intercellular signaling and in connecting cells with the extracellular matrix. May take part in the regulation of cell motility, growth and differentiation. Binds hyaluronic acid.
Synonyms: GHAP; CSPG2; PG-M; ERVR; WGN; WGN1
Tractability: Antibody: UniProt places it where antibodies can reach, with high confidence; its Gene Ontology location is reachable by antibodies, with high confidence; UniProt predicts a signal peptide or a membrane-spanning region. PROTAC: ubiquitination databases record sites on it; its protein half-life has been measured.
Gene: Protein-coding gene on chromosome 5 (83,471,618 to 83,582,303, forward strand). Ensembl gene ENSG00000038427.
Subcellular location: Secreted, extracellular space, extracellular matrix; Cell projection, cilium, photoreceptor outer segment; Secreted, extracellular space, extracellular matrix, interphotoreceptor matrix; Secreted
Subcellular location (Human Protein Atlas): End piece; Mid piece; Principal piece; Vesicles; Predicted to be secreted
Pathways (Reactome):
Disease: Defective B3GALT6 causes EDSP2 and SEMDJL1; Defective B3GAT3 causes JDSSDHD; Defective B4GALT7 causes EDS, progeroid type; Defective CHST14 causes EDS, musculocontractural type; Defective CHST3 causes SEDCJD; Defective CHSY1 causes TPBS
Metabolism: CS-GAG biosynthesis; CS/DS degradation; DS-GAG biosynthesis; Glycosaminoglycan-protein linkage region biosynthesis
Metabolism of proteins: Post-translational protein phosphorylation; Regulation of Insulin-like Growth Factor (IGF) transport and uptake by Insulin-like Growth Factor Binding Proteins (IGFBPs)
Extracellular matrix organization: ECM proteoglycans
Gene Ontology:
Molecular function: protein binding; protein tyrosine phosphatase activator activity; extracellular matrix structural constituent conferring compression resistance; glycosaminoglycan binding; hyaluronic acid binding; calcium ion binding
Biological process: osteoblast differentiation; cell adhesion; cell recognition; central nervous system development; skeletal system development; system development
Cellular component: extracellular matrix; extracellular region; membrane; endoplasmic reticulum lumen; gel phase of interstitial matrix; Golgi lumen; lysosomal lumen; microfibril; perineuronal net; synapse; interphotoreceptor matrix; photoreceptor outer segment
Genetic constraint (gnomAD): Loss-of-function variants: 43 observed, 248.76 expected, observed/expected ratio (o/e) 0.17, 90% interval 0.13 to 0.22. The upper end of that interval is the gene's LOEUF score, 0.22, which puts it in group 1 of 6, group 1 being the genes least tolerant of losing a copy. Missense variants: 3,673 observed, 4,145.9 expected, observed/expected ratio (o/e) 0.89, 90% interval 0.86 to 0.91. Synonymous variants: 1,367 observed, 1,474.8 expected, observed/expected ratio (o/e) 0.93, 90% interval 0.89 to 0.97.
Gene-disease validity (ClinGen):
ClinGen rates the evidence that VCAN causes each of these diseases.
Wagner disease (autosomal dominant): Definitive. Wagner disease is a rare hereditary vitreoretinopathy characterized by an anomaleous vitreous associated with myopia, cataract, chorioretinal atrophy, and peripheral tractional or rhegmatogenous retinal detachment.
Homologues: Orthologues: chimpanzee VCAN (99% identical), macaque VCAN (94% identical), dog VCAN (75% identical), pig VCAN (75% identical), rabbit VCAN (66% identical), mouse Vcan (63% identical), rat Vcan (61% identical), tropical clawed frog vcan (31% identical), zebrafish vcanb (18% identical), zebrafish vcana (12% identical). Paralogues in human: ACAN (18% identical), NCAN (12% identical), BCAN (10% identical), HAPLN3 (4% identical), HAPLN1 (4% identical), HAPLN4 (4% identical), HAPLN2 (3% identical).
Diseases named in the same sentence as VCAN in open-access papers:
VCAN is named in the same sentence as 270 diseases in open-access papers, as found by Europe PMC text mining. Sharing a sentence is not in itself a finding about the gene and the disease. The quoted sentences say what the papers report.
breast carcinoma (78 papers, 2007 to 2026). "This upregulation of VCAN has been associated with more aggressive disease and poorer outcomes for breast cancer patients." (PMID 40361362, 2025). "In breast cancer, VCAN production is partially driven by cancer-associated fibroblasts under the influence of cancer cells, potentially through TGF-β signaling." (PMID 40361362, 2025). "Recent reports have discovered that VCAN-high breast cancers have a greater infiltration of tumor-associated macrophages, a critical piece of the immunosuppressive landscape of many solid tumors." (PMID 40361362, 2025). "To demonstrate the correlation of VCAN with cancer-associated fibroblast (CAF) associated genes in breast cancer, we conducted gene expression analyses across the TCGA PanCancer database for invasive breast carcinoma." (PMID 40361362, 2025). "Researchers have reported positive associations between high tissue expression of VCAN and poor survival outcomes in various malignancies including breast cancer and renal cell carcinoma." (PMID 36669591, 2023). "Expression of interstitial VCAN is associated with the accumulation of tumor-related macrophages and the pro-inflammatory and pro-angiogenic state of primary tumors in advanced breast cancer." (PMID 36842141, 2023). "In a study involving 4T1 mouse mammary carcinoma, it was found that the expression level of VCAN is related to the number of tumor-associated macrophages (TAM) in the tumor microenvironment and can promote lung lymph node metastasis." (PMID 37108649, 2023). "For instance, versican was observed in various types of malignancies, including breast cancer, prostate cancer, and HCC, where it is associated with high rates of cancer relapse and poor outcomes." (PMID 33809195, 2021). "We found associations between VCAN rs11726 A>G genotype and BGN (rs743641 (251A>T) – rs743642 (318G>T)) – VCAN rs11726 (1429A>G) inferred allele combinations, and shoulder pain/disability among women following breast cancer treatment." (PMID 34162438, 2021). "Previous studies showed that VCAN was closely associated with the proliferation and metastasis of various types of tumor cells, such as gastric cancer, leukaemia and breast cancer cells." (PMID 34404882, 2021). "In the 4T1 breast cancer mouse model, expression and distribution of versican positively associated with increased peri-tumoral TAM recruitment and breast cancer progression." (PMID 32283687, 2020). "Hyaluronan as well as versican also accumulate in the breast cancer ECM and are associated with poor prognosis." (PMID 32984031, 2020). "Taken together, our data in mice and canine mammary tumors suggest an intrinsic association between stromal versican expression and TAMs infiltration with breast cancer progression and invasion." (PMID 31334111, 2019). "A forced spirometry technique was used to evaluate the physiological changes in lung function caused by the metastatic development and versican accumulation in lung parenchyma during 4T1 breast cancer metastasis." (PMID 31334111, 2019). "The proteoglycan versican is one of the most studied components of the extracellular matrix associated with human breast cancer." (PMID 23082892, 2012). "The deposition of versican in tumor stroma is significantly higher in MAMCs, a mammographic finding that is associated with higher risk for breast cancer than increased MD alone." (PMID 21791066, 2011). "In human tumors, versican is detected in the interstitial tissues at the invasive margins of breast carcinoma and in the elastic tissues associated with tumor invasion." (PMID 21079779, 2010). "Increased versican expression has been associated with local breast cancer invasiveness and a more aggressive tumor phenotype." (PMID 17662123, 2007). "VCAN has demonstrated relevance over several “hallmarks of cancer” and has been implicated in modulating both cancer cell-intrinsic and microenvironment properties in breast cancer." (PMID 40361362, 2025).
breast carcinoma (continued). "The study suggests that the coexpression of versican with these receptors is associated with more aggressive characteristics of mammary tumors in female dogs, indicating that versican may play a significant role in tumor progression." (PMID 40005948, 2025). "Many studies have found that VCAN may be a risk factor in gastric cancer, breast cancer, and colorectal cancer." (PMID 36407083, 2022). "One unexpected finding was the correlation between increased Vcan RNA expression and better DMFS in ERpos and LNneg cancers as VCAN protein expression in peritumoral stroma of the breast has previously been associated with poor prognosis in LNneg breast cancers." (PMID 34565423, 2021). "Moreover, the role of Versican in modulating the loss of adhesion and cell motility has also been recognized in cases of breast cancer metastasis or ovarian cancers." (PMID 26515726, 2015). "Some studies also suggest that versican is involved in cancer development and progression because higher expression levels have been associated with local invasion and angiogenesis in breast cancer in women." (PMID 23082892, 2012). "Overexpression of EGFR and versican has been reported in association with breast cancers." (PMID 22096483, 2011). "In summary, versican is implicated in local tumor invasiveness in human breast carcinoma." (PMID 17662123, 2007). "Due to our findings correlating biological significance in breast cancer with only the detectable/undetectable status of VCAN, we assessed VCAN proteolysis utilizing the detectable/undetectable designation for both VCAN and αDPEAAE." (PMID 40361362, 2025). "The upregulation of VCAN is closely correlated with promoter methylation and the clinical features of breast cancer patients." (PMID 41348904, 2025). "Interestingly, our work identified that the association between VCAN and immune infiltration is consistent across breast cancer subtypes, indicating a potential to identify patients that may derive benefit from immunotherapy outside of the already approved TNBC subtype." (PMID 40361362, 2025). "Based on these findings, VCAN detection should be explored as a biomarker for all breast cancer patients receiving immunotherapy and chemotherapy, including the neoadjuvant and metastatic settings." (PMID 40361362, 2025). "Studies suggest that the breast cancer patient’s survival rate gets lower when the VCAN expression level gets higher." (PMID 41348904, 2025). "Whereas previous reports have demonstrated a difference in total CD8+ T cells in breast cancers across stage, age and menopause status, our findings indicate that a VCAN-status predicts more total CD8+ T cells across each of these clinical groups." (PMID 40361362, 2025). "Our work corroborated these findings by showing that the vast majority of breast cancers have significant VCAN accumulation." (PMID 40361362, 2025). "We find a strong inverse correlation between versican accumulation and lymphocyte infiltration, warranting further investigation into versican as a potential biomarker of immunotherapy response in breast cancer." (PMID 40361362, 2025). "Next, the expression of VCAN was assessed across the clinical subtypes of breast cancer using the TCGA dataset." (PMID 40361362, 2025). "VCAN has been shown to have prognostic value in breast cancer, as patients with elevated VCAN expression demonstrated a higher relapse rate and reduced overall survival rates." (PMID 40361362, 2025). "Regarding well-studied lecticans, involvement of VCAN in cancer metastasis has been reported in prostate cancer, testicular germ cell tumours (GCTs), breast cancer, and lung cancer." (PMID 38791985, 2024). "Although VCAN is considered one of the most studied ECM components in human breast cancer, little is known about the influence of its proteolysis on tumor progression." (PMID 39682243, 2024). "In breast cancer, the VCAN G3 domain interacts with ECM components, including fibronectin and VEGF, to promote angiogenesis." (PMID 38791985, 2024).
breast carcinoma (continued). "Meanwhile, such angiogenesis‐related VCAN+ macrophage subset was also identified in breast cancer and melanoma." (PMID 39422697, 2024). "Due to the similarities between humans and canines, canine mammary tumors are a valuable model for studying VCAN proteolysis in tumor microenvironments." (PMID 39682243, 2024). "Our study suggests, for the first time, in the context of mammary cancer in a canine model, that VCAN proteolysis is an important player in the tumor microenvironment, associated with invasiveness and reduced deposition of type III collagen." (PMID 39682243, 2024). "It has also been reported that VCAN can enhance the migration and invasion of breast cancer cells by promoting Snail-mediated EMT." (PMID 37461061, 2023). "In contrast to the complex phenotypes of tumor-associated macrophages (TAMs) in the breast cancer and lung cancer TMEs, the TAMs in HCC exhibited remarkable dichotomy (VCAN+ TAMs and C1QC+ TAMs)." (PMID 37383234, 2023). "The expression of VCAN stimulates arterial smooth muscle cells, promoting the growth and metastasis of breast cancer cells, and has an anti-apoptotic effect, reducing cell death caused by oxidative stress." (PMID 37108649, 2023). "The expression of bone homing inductors of the circulating breast cancer cells, also identified as bone metastasis markers in breast cancer, such as Versican, Osteopontin, and Prolactin receptor, were investigated." (PMID 36499741, 2022). "It was reported that the major source of VCAN protein was constituted by CAFs in breast cancer, colon cancer, pharyngeal cancer, ovarian cancer and prostate cancer." (PMID 36203562, 2022). "Suppressed VCAN expression blocks breast cancer cell self-renewal, while overexpression of the G3-domain of VCAN promotes cancer cell self-renewal via the EGFR/AKT/GSK3β pathway." (PMID 36358747, 2022). "Versican is a proteoglycan that is an essential structural factor of the extracellular matrix overexpressed in aggressive breast cancer." (PMID 36499741, 2022). "For instance, in breast cancer cells, VCAN V2 expression suppressed Snail and induced E-cadherin protein levels through inhibition of the EGFR/ERK/GSK3β axis." (PMID 36358747, 2022). "Our study is first to report that VCAN rs11726, independently or interacting with BGN polymorphisms, is associated with shoulder pain or disability in breast cancer survivors." (PMID 34162438, 2021). "More recently, Li and colleagues illustrated that miR-543 through suppression of VCAN impaired breast cancer cell proliferation, migration, and invasion." (PMID 34787051, 2021). "For instance, Oskarsson and co-workers have proved that ECM proteins like Tenascin-C (TNC) and Versican (VCAN) play a critical role during the earliest stage of breast cancer metastasis to the lungs." (PMID 33418894, 2021). "Breast cancer cells expressing the chondroitin sulfate proteoglycan member versican G3-domain exhibit enhanced migration and invasion to primary bone stromal cells or osteoblasts in part via the epidermal growth factor receptor (EGFR)/AKT axis." (PMID 34064589, 2021). "That study analysed a mix of 60 grade 1–3 breast cancers in total with six showing increased VCAN staining." (PMID 34565423, 2021). "Such a dual function was reported in a study investigating the role of cancer cell-derived versican in colorectal versus breast cancer cells." (PMID 33466303, 2021). "Versican also plays an essential role in the structural architecture of vascular walls, and is upregulated in breast cancer, regulating tumor growth by promoting angiogenesis." (PMID 33163489, 2020). "Versican V4 is the newest isoform of versican, which has been identified so far in breast cancer and contains a shortened GAGβ region." (PMID 32150898, 2020). "Tumor associate macrophages (TAMs) participate in the regulation of murine signaling 4T1 breast cancer mode by versican implies the potential of versican as an attractive target for breast cancer therapy." (PMID 32742634, 2020).
breast carcinoma (continued). "High expression of versican enhanced cell migration and metastasis in several breast cancer cell lines." (PMID 32825245, 2020). "It has been found in various breast cancer models that versican is involved in tumor occurrence and metastasis." (PMID 32742634, 2020). "Experiment have shown that elevated levels of PAPSS2 and versican are essential for snail-mediated breast cancer cell migration and metastasis." (PMID 32742634, 2020). "The stromal versican expression was correlated with TAMs accumulation in tumors with an advanced stage from spontaneous canine mammary carcinoma samples." (PMID 31334111, 2019). "In breast cancer, the interaction between stromal versican deposition and neoplastic cells was previously shown as an important step in tumorigenesis." (PMID 31334111, 2019). "In conclusion, stromal versican expression was found in primary canine and murine breast cancer models." (PMID 31334111, 2019). "Here we highlighted the correlation between versican expression, TAMs accumulation and tumor progression using two models of mammary carcinomas: spontaneous mammary carcinoma in dogs and mammary carcinoma implanted in mice." (PMID 31334111, 2019). "We next examined the expression of versican and TAMs infiltration evaluated in the primary tumor and metastatic lung of the 4T1 murine model of breast cancer to investigate their role during cancer progression and metastasis." (PMID 31334111, 2019). "Versican expression also correlates with increase metastasis and pulmonary dysfunction, suggesting the involvement of TAMs in regulating important steps during murine 4T1 breast cancer model development through versican signaling." (PMID 31334111, 2019). "We first examined the expression of versican and TAMs infiltration in 108 spontaneous canine mammary neoplasms." (PMID 31334111, 2019). "We also analyzed 7 breast cancer cases (3 from Group 2/nulliparous women, 2 from Group 3/early pregnancy and 2 from Group 5/late pregnancy) with immunohistochemistry against PR, Versican, Wnt4, CD15 and β-Catenin." (PMID 28423605, 2017). "In the present study, we performed immunohistochemistry for PR, Wnt4, Versican, β-catenin and CK-15 on breast tissue from different subpopulations of women, stratified according to age at first pregnancy and occurrence of breast cancer." (PMID 28423605, 2017). "We collected benign breast tissue of 125 women who had been stratified according to age at first pregnancy and the occurrence of subsequent breast cancer, and performed immunohistochemistry for PR, Wnt4 and the Wnt-target Versican." (PMID 28423605, 2017). "Despite the small sample size, we demonstrated a relationship between a higher expression of certain components of the Wnt pathway, such as PR, Wnt4 and Versican, and the occurrence of subsequent breast cancer." (PMID 28423605, 2017). "It had been demonstrated that overexpression of versican by G3 domain-containing EGF-like motifs enhanced breast cancer self-renewal through EGFR/AKT/GSK3β signaling, and increased resistance to chemotherapy." (PMID 27490467, 2016). "Angiogenesis in astrocytoma and breast cancer was suggested to result from interaction between VCAN and VEGF." (PMID 26873137, 2016). "For instance, the versican 3′UTR has been identified to play different roles in breast cancer and HCC." (PMID 26872371, 2016). "Versican has been observed in many malignancies, including melanoma, epithelial ovarian cancer, breast cancer and non-small cell lung cancer, implying its importance in tumor maintenance." (PMID 26619403, 2015). "Inhibiting versican production by CD11b+ BDMCs radically decreased the burden of lung metastases in a mouse model of spontaneous breast cancer, specifically preventing the progression from micrometastases to macrometastases." (PMID 26539408, 2015).